INS (insulin)
Diseases named in the same sentence as INS in open-access papers (continued):
Sharing a sentence is not in itself a finding about the gene and the disease.
Insulin resistance (continued). "Hepatic insulin resistance is defined as raised basal hepatic glucose production in the presence of normal or raised plasma insulin levels, suggesting a failure of normal suppression of hepatic glucose production." (PMID 38292764, 2023). "Insulin resistance refers to a pathological state in which insulin-sensitive organs become resistant to insulin and reflects disruption of metabolic homeostasis." (PMID 38057801, 2023). "Pioglitazone is an insulin resistance inhibitor widely used as monotherapy or combined with metformin or insulin." (PMID 37095270, 2023). "The product of fasting glucose x fasting insulin (HOMA-IR) is routinely used to stratify individuals with obesity by their degree of insulin resistance and has been shown to be predictive of individual responses to dietary intervention." (PMID 37402955, 2023). "A study using homeostatic model assessment of insulin resistance (HOMA-IR) observed an adverse correlation between blood insulin levels and total SCFAs, including acetate and propionate." (PMID 36900540, 2023). "The activation of Nrf2 can improve insulin sensitivity in the peripheral tissues and prevent the development of insulin resistance." (PMID 38107110, 2023). "Type 2 diabetes (T2DM) is a metabolic disease characterized by elevated serum glucose concentrations due to insulin resistance and impaired insulin secretion." (PMID 37298483, 2023). "Our study lasted 6 years and therefore the pancreas was unable to compensate for increasing insulin resistance over a long time resulting in a decrease of insulin secretion." (PMID 37795366, 2023). "Homeostatic Model Assessment of Insulin Resistance (HOMA-IR) is a method for assessing insulin resistance from fasting insulin and fasting glucose concentration." (PMID 37072577, 2023). "It is also established that low nocturnal secretion of 6-sulfatoxymelatonin inversely correlates with insulin resistance and insulin values in individuals with prediabetes." (PMID 37371675, 2023). "hsa-miR-21-5p expression was positively correlated with serum AFP, insulin, and insulin resistance (r = 0.5, p < 0.001, r = 0.334, p = 0.01, and r = 0.303, p = 0.02, respectively)." (PMID 36834570, 2023). "The majority of found diabetes loci in Caucasians and Asians are associated with impaired pancreatic β-cell function; meanwhile, only a few are found which are related to insulin resistance or fasting insulin levels." (PMID 37298715, 2023). "Generally, the initial event in the development of T2DM is increased peripheral insulin resistance, which is characterized by a decreased response of the body to insulin." (PMID 37761031, 2023). "Unexpectedly, expression markers of key enzymes of gluconeogenesis were decreased in WD-fed mice when compared with CD-fed mice, suggesting preserved insulin action in insulin resistance partially compensated by hyperinsulinaemia." (PMID 36525084, 2023). "Insulin resistance induced by GCs can result from an alteration in the molecules involved in the insulin signaling cascade." (PMID 37560158, 2023). "In PTDM, both decreased insulin secretion by pancreatic β-cells and tissue insulin resistance were observed." (PMID 37628646, 2023). "The fasting insulin to glucose ratio, an index of insulin resistance, was markedly reduced following STZ treatment, but an improvement was noted upon treatment with HWE and HEE." (PMID 37175224, 2023). "It significantly improved the lipid panel, decreased the body weight, lowered the serum insulin and glucose levels, ameliorated the insulin resistance status, and decreased the serum level of lipase and amylase." (PMID 36915161, 2023). "Ceramides block the normal conduction of the insulin signaling pathway by increasing the secretion of pro‐inflammatory cytokines, resulting in the body being in a state of insulin resistance." (PMID 37612254, 2023).
Insulin resistance (continued). "Type 2 diabetes, on the other hand, begins with insulin resistance, which is the insufficiency of insulin secretion in the body and the inability of cells to respond to insulin correctly." (PMID 37048331, 2023). "DM is the most prevalent metabolic disease characterized by impairment in insulin release, insulin resistance, and hyperglycemia." (PMID 38131990, 2023). "Patients with PHE-induced hyperglycemia have an increased insulin requirement which suggests the occurrence of insulin resistance." (PMID 37334286, 2023). "They control glycemic changes, induce insulin resistance, increase triglyceride synthesis, and decrease fatty acid oxidation by interfering with insulin signaling." (PMID 37836471, 2023). "Skeletal muscle insulin resistance is characterized by a reduced ability of insulin to stimulate glucose uptake and glycogen synthesis." (PMID 37511225, 2023). "A relationship between atypical antipsychotics and both hyperglycaemia and DM is widely acknowledged, with proposed mechanisms for its pathogenesis including insulin resistance, decreased insulin secretion from β-cells, and dysfunctional leptin action." (PMID 37139329, 2023). "At the end of the prediabetes induction period (20 weeks), body weights, fasting blood glucose (FBG), plasma insulin and insulin resistance were assessed in the NPD and PD groups." (PMID 38024366, 2023). "Impairment of this pathway produces metabolites that reduce the bioactivity of insulin and lead to insulin resistance, a symptom of T2DM." (PMID 38313181, 2023). "Typically, the maternal pancreas exhibits increased insulin production as a means of counteracting insulin resistance." (PMID 37724233, 2023). "We investigated the effects of empagliflozin on insulin resistance, insulin sensitivity and β-cell function indexes in patients with a recent acute coronary event and newly detected dysglycaemia, i.e., impaired glucose tolerance (IGT) or T2DM." (PMID 37568149, 2023). "Type 2 diabetes mellitus (T2DM) is characterized by a range of physiological factors, including insulin resistance, impaired insulin secretion, excess body fat, reduced incretin effect, heightened glucagon release, and abnormal lipid levels." (PMID 37779743, 2023). "In patients with insulin resistance, insulin sensitivity is reduced, the efficiency of glucose uptake and utilization decreases, and the body compensatorily secretes excess insulin, inducing the development of hyperinsulinemia." (PMID 38260162, 2023). "This study aimed to elaborate on the significant relations of COVID-19 infection with body fat distribution, changes in serum insulin, and homeostasis model assessment-estimated insulin resistance (HOMA-IR) levels before and after the infection." (PMID 36843827, 2023). "Insulin resistance (IR) is defined clinically as the inability of a known quantity of exogenous or endogenous insulin to increase glucose uptake and utilization in an individual to an extent corresponding to that in the average population." (PMID 36793924, 2023). "Our finding indicated the increased levels of serum FBS, HbA1c, insulin, and insulin resistance, as well as older age, in diabetic men." (PMID 37208686, 2023). "Gremlin 1 suppresses insulin action in primary adipocytes and attenuates basal- and insulin-stimulated glucose uptake, implying a role of Gremlin 1 in insulin resistance in obesity." (PMID 37965235, 2023). "Activation of mTORC1 by leucine can lead to the uncoupling of insulin signalling at an early stage, potentially contributing to insulin resistance." (PMID 37842639, 2023). "Despite excluding pregnant women with diagnosed gestational diabetes mellitus (GDM), many of the metabolic pathways we found to be upregulated in ICP were related to type II diabetes mellitus, insulin resistance, and insulin secretion." (PMID 38260149, 2023).
Insulin resistance (continued). "In cell culture studies of neuronal cells, insulin suppressed phosphorylation of amyloid precursor protein and in a fat-fed murine model of metabolic syndrome, induction of insulin resistance abolished the inhibitory effect of insulin." (PMID 36875491, 2023). "Another tissue that shows an impaired response to insulin signaling in scenarios of insulin resistance and diabetes is muscle." (PMID 37822597, 2023). "Social jet lag was related to a lower HDL-cholesterol level, higher triglycerides, higher fasting plasma insulin, insulin resistance, and adiposity." (PMID 36984810, 2023). "The increase in adipose tissue mass serves as a protective mechanism for insulin-sensitive tissues, including the liver, skeletal muscle, and, potentially, pancreatic beta cells, shielding them from insulin resistance." (PMID 37376225, 2023). "Data confirms that PP1γ isoform of PP1 serine-threonine phosphatase regulate neuronal insulin signaling and insulin resistance." (PMID 37085815, 2023). "HOMA‐R calculated from fasting blood glucose and insulin, which is an insulin resistance marker, in the male EOD‐1 group was significantly lower than in the male placebo group by ANCOVA." (PMID 36789056, 2023). "In the rodent model, brain insulin resistance occurred even after one day of high-fat diet feeding, contributing to subsequent hepatic insulin resistance." (PMID 37960324, 2023). "ADT has been shown to be associated with increased fasting glucose levels, elevated serum insulin and insulin resistance, including the diagnosis of diabetes mellitus." (PMID 37335291, 2023). "Insulin resistance is defined as the “inability of insulin to increase cellular glucose uptake and utilization, leading to compensatory hyperinsulinemia”." (PMID 37759253, 2023). "We have previously reported that thermal stimulation of SMDC changed the expression of genes involved in improving insulin resistance by promoting glucose uptake through various insulin-dependent and independent mechanisms." (PMID 37238736, 2023). "The main characteristic of T2DM is insulin resistance and compensatory inadequate insulin secretion, resulting in elevated blood glucose levels." (PMID 37569372, 2023). "Long-term high-level of FBG can make the blood insulin content increase continuously, thus inducing hyperinsulinemia, further inducing insulin resistance, and ultimately inducing the disorder of glucose metabolism and reproductive hormones." (PMID 37189071, 2023). "Other biochemical parameters, including FBG, serum insulin, and antioxidant enzyme assays, also showed that antioxidant vitamins reduce glyphosate-induced insulin resistance and type-2 diabetes." (PMID 38274944, 2023). "Metabolic derangements caused by insulin resistance, such as GDM and T2DM, are closely linked to the aging process, as the whole-body intracellular responses to insulin tend to progressively decrease with age, often resulting in glucose intolerance." (PMID 37109166, 2023). "The insulin resistance was measured by reduced insulin-mediated glucose uptake and glycogen synthesis and indicated by diminished phosphorylation of protein kinase B (AKT) Ser-473." (PMID 38203642, 2023). "Diet reversal reduced plasma insulin concentration and insulin resistance and increased insulin sensitivity to levels comparable to age-matched mice fed only the normal diet." (PMID 36674448, 2023). "Genetic instruments of insulin resistance were derived from the GWASs by Meta‐Analyses of Glucose and Insulin‐related traits Consortium and Global Lipids Genetics Consortium." (PMID 37403750, 2023). "TNF-α and IL-6 are considered the main inflammatory mediators of insulin resistance, which can activate various inflammatory signaling pathways, inhibit insulin signaling, and lead to insulin resistance." (PMID 36986084, 2023).
Insulin resistance (continued). "Some studies have suggested that under conditions of iron overload, decreased levels of adiponectin and increased secretion of leptin reduce the sensitivity of adipocytes to insulin and lead to insulin resistance (IR)." (PMID 38260171, 2023). "Its defective expression or translocation leads to the decreased insulin-stimulated glycogen synthesis, thereby contributing to insulin resistance in individuals with type 2 diabetes." (PMID 37907988, 2023). "The study’s findings revealed that the combined effects of preserving beta pancreatic cells, enhancing insulin production, and reducing insulin resistance played pivotal roles in mitigating gestational complications associated with G-DM in pregnant mice." (PMID 37893486, 2023). "It has been reported that reductions in insulin levels and AUCglucose values are related to improvements in insulin resistance." (PMID 37372530, 2023). "At the cellular level, insulin resistance implicates a disruption in insulin signaling pathways, leading to impaired glucose uptake and metabolism." (PMID 38203517, 2023). "Thirty-eight studies reported on the associations of helminths with metabolic syndrome and related measures, such as BMI, WC, WHR, glucose intolerance, insulin level, and/or homeostatic model assessment for insulin resistance (HOMA-IR)." (PMID 36827239, 2023). "Klotho induced insulin resistance in adipocytes by regulation of glucose transporter type 4 and intracellular insulin signalling through AKT43." (PMID 37985893, 2023). "In Hispanic youth with overweight, increased insulin resistance and a higher acute insulin response have led to β-cell deterioration, which can lead to the development of T2D." (PMID 37689792, 2023). "Insulin resistance is mainly due to the interference in normal insulin signaling by decreasing the expression of insulin receptors, IRS1 and IRS2." (PMID 37014444, 2023). "The idea of the potential involvement of vitamin D in the etiology of T2DM was created as a result of the simultaneous link between VDD and insulin resistance, decreased insulin production, and their significant metabolic repercussions." (PMID 38073984, 2023). "Insulin resistance (IR) refers to a condition in which target organs that insulin acts upon are less sensitive to insulin’s action, resulting in less than normal biological effects despite a normal dose of insulin." (PMID 37248537, 2023). "On the other hand, there is a well-recognized relationship between obesity and insulin resistance, with insulin sensitivity improving when obese patients lose weight and return to normal weight." (PMID 36996012, 2023). "Akt phosphorylation/activation is a key step in the insulin signaling cascade, leading to increased glucose uptake by muscle cells, and is impaired in insulin resistance." (PMID 36982168, 2023). "Insulin-sensitizing agents, represented by metformin, are beneficial for alleviating insulin resistance, menstrual irregularities, hirsutism, anovulation, and obesity." (PMID 37525285, 2023). "The majority of these processes were found to be downregulated, likely due to weak insulin signaling in peripheral tissues in the setting of insulin resistance." (PMID 36979367, 2023). "Tacrolimus can degenerate pancreatic ducts, reduce the number of β cells, cause cytoplasmic swelling and vacuolization, and induce apoptosis, resulting in decreased insulin synthesis and secretion and insulin resistance." (PMID 36843576, 2023). "Increased insulin sensitivity occurs in early pregnancy, followed by progressive insulin resistance, increased lipid synthesis, and decreased protein catabolism." (PMID 38275628, 2023). "This measurement allowed us to obtain an alternative estimate of adipose insulin resistance in our patient: the product of serum fasting triglycerides (mg/dL) times serum fasting insulin (mU/L)." (PMID 38260129, 2023).
Insulin resistance (continued). "Similar to rosiglitazone, Peptide 2 supplementation improved systemic insulin resistance during the hyperinsulinemic-euglycemic clamp and enhanced insulin signalling in white adipose tissue, modulating ex vivo lipolysis." (PMID 36837793, 2023). "Numerous studies have suggested that reduced levels of vitamin D disrupt insulin sensitivity, beta-cell function, or both to cause the onset of T2DM and insulin resistance." (PMID 36742396, 2023). "The decrease in insulin resistance typically leads to a reduction in plasma insulin and glucose levels following vitamin D supplementation, as observed in previous studies." (PMID 38137858, 2023). "Many studies have demonstrated the role of SGLT2 inhibitors in improving insulin resistance and increasing insulin sensitivity." (PMID 37691190, 2023). "Over time, on HFD, the severity of insulin resistance in apoA-IV−/− mice increased, positively correlated to the changes in basal insulin levels." (PMID 38004234, 2023). "Studies have shown that melatonin can help regulate glucose homeostasis by improving insulin sensitivity and reducing insulin resistance." (PMID 37113302, 2023). "Insulin resistance, characterized by an attenuation of the metabolic actions of insulin in the liver, skeletal muscle, and adipose tissue, results from an imbalance between energy intake and expenditure." (PMID 38201252, 2023). "Recombinant resistin administration to normal animals produce insulin resistance, however, immune neutralization of resistin improves insulin sensitivity in obese animals with insulin resistance." (PMID 37014444, 2023). "For example, hyperosmotic stress of adipocytes was reported to inhibit insulin signaling and induce insulin-resistance." (PMID 38115136, 2023). "Overall, this study has important implications for the potential use of CRHR2 antagonists for treatment of insulin resistance and offers insights into the molecular relationship between insulin’s effects and GPCR signal transduction." (PMID 37402735, 2023). "The homeostatic model assessment (HOMA)-insulin resistance (IR) index was calculated from fasting glucose and insulin levels, supporting the remarkable prevention of insulin resistance by CHP administration." (PMID 37600955, 2023). "Insulin resistance results in reduced glucose uptake by impairing insulin signaling, which is consistent with our results; that is, LPS, TNFα, and IFNγ (LTI) treatment markedly suppresses glucose uptake and Akt activation." (PMID 36771210, 2023). "The circulating adiponectin levels decrease correspondingly throughout pregnancy in correlation with increasing insulin resistance and insulin sensitivity, and adiponectin levels are low in patients with GDM." (PMID 38203346, 2023). "The hepatic SREBP1 signals increased from 2nd to 6th week, but decreased at 8th week due to substantiated insulin resistance (plasma insulin levels, plasma glucose levels, and P-AKTSer473 levels) in HCD group." (PMID 37520290, 2023). "In ob/ob mice, deletion of TNFα or obesogenic diet leads to a reduction in insulin resistance and improvement in insulin signaling in the WAT and muscles." (PMID 37755259, 2023). "As expected, HFD induced increase in insulin secretion and thus increased insulin resistance as presented by HOMA-IR, though the increment was similar among both groups." (PMID 37845387, 2023). "The constructed NA-FGF-N-2-HACC/CMCS MPs can be used as a novel drug agent to replace traditional insulin-based therapy in the treatment of type 2 diabetes and provide a theoretical basis for addressing insulin resistance." (PMID 37514488, 2023). "Conversely, increased expression of PGC-1α in skeletal muscle is known to ameliorate metabolic factors, such as insulin sensitivity and insulin resistance." (PMID 37041517, 2023).